STAT3 (signal transducer and activator of transcription 3)
Diseases named in the same sentence as STAT3 in open-access papers (continued):
Sharing a sentence is not in itself a finding about the gene and the disease.
ovarian carcinoma (continued). "CD133+ ovarian cancer stem cells cultured on a cell culture matrix formed fluid-conducting tube networks activated NF-κB and STAT3 signal pathways, through autocrine chemokine (C-C motif) ligand 5 (CCL5) upregulation promoting differentiation into endothelial cells." (PMID 31861720, 2019). "Together, these results revealed for the first time that Pect‐MCP could be considered as a potential drug to enhance the PTX effect on ovarian cancer cells MCTS through inhibition of STAT3 activity." (PMID 31197964, 2019). "Taken together, this study showed for the first time that Gal‐3 expression is higher in MCTS vs monolayer ovarian cancer cells which may contribute to paclitaxel resistance through STAT3 activation." (PMID 31197964, 2019). "Next, we characterized the transcription signature of STAT3 in multiple ovarian cancer cells." (PMID 31534498, 2019). "Previous reports have used combined inhibition of activated STAT signaling pathways and IL-6 as a therapeutic approach against drug-resistant cells, and other studies have shown that Taxol resistance in ovarian cancer can be overcome by inhibiting IL-6 and STAT3." (PMID 31601188, 2019). "Moreover, the overexpression of miR‐92a was associated with worse survival in a mouse model of intraperitoneal ovarian cancer, because it targeted signal transducer and activator of transcription 3 (STAT3) signaling." (PMID 29266846, 2018). "To understand whether inhibition of the STAT3 pathway could enhance the anti-tumor activity of chemotherapy reagents, we incubated human ovarian cancer cells with several chemotherapy agents, either alone or in combination with ruxolitinib." (PMID 29849942, 2018). "Leptin is also believed to influence cancer prognosis by promoting cancer cell migration and invasion through leptin mediated activation of JAK/STAT3, and by promoting focal adhesion formation, maintenance of stemness and mesenchymal phenotypes in ovarian cancer cells." (PMID 29662629, 2018). "We aimed to evaluate the implication of the p110 alpha PI3K subunit in ovarian cancer chemoresistance acquisition, and to evaluate whether the STAT3 pathway can mediate resistance to PI3K inhibitors through secretion of IL6." (PMID 29930760, 2018). "For example, the lncRNA named MEG3 was recently implicated as an influencer of the signal transducer and activator of transcription 3 (STAT3) expression, by altering miR-21 expression in ovarian cancer; it has been shown to function as a tumor suppressor in many cancer types." (PMID 29596364, 2018). "Interestingly, highly invasive ovarian cancer cells showed more remarkable glutamine dependence than low-invasive ovarian cancer cells; this feature is related to glutamine-mediated STAT3 (signal transducer and activator of transcription 3) modulation." (PMID 29966227, 2018). "Activation of STAT3 by microenvironmental IL-6 can also induce EMT in ovarian cancer cells." (PMID 30380628, 2018). "In addition, increased STAT3 activation occurs in paclitaxel-resistant ovarian cancer cells, and STAT3 inhibition potently increases anti-tumor activity of paclitaxel." (PMID 29849942, 2018). "The STAT3 pathway has been shown to be a prerequisite for the proliferation and maintenance of glioblastoma and breast cancer stem cells, rapidly cycling intestinal stem cells, as well as ovarian cancer cells." (PMID 29682172, 2018). "Previous studies suggest that activation of STAT3 may confer cell resistance to chemotherapy reagents in ovarian cancer cells." (PMID 29849942, 2018). "Targeting JAK1/STAT3, therefore, could be a potential novel therapeutic approach for treating advanced and chemoresistant ovarian cancer." (PMID 29849942, 2018). "Targeting JAK/STAT3, therefore, could be a potential novel therapeutic approach for treating advanced and chemoresistant ovarian cancer." (PMID 29849942, 2018).
ovarian carcinoma (continued). "STAT3 activation by Paclitaxel, via the induction of reactive oxygen species, has been demonstrated in several tumor types; however, this phenomenon is cell-type-specific, and conflicting effects on STAT3 expression in response to Paclitaxel have been reported in ovarian cancers." (PMID 30127274, 2018). "In summary, our results demonstrate that pterostilbene, a resveratrol analog with improved bioavailability, reduces proliferation and migration in ovarian cancer cells involving inhibition of the STAT3 pathway, and potentiates the anti-proliferative effects of cisplatin." (PMID 29986501, 2018). "Our study demonstrated that c-Src contributed to hypoxic microenvironment-rendered paclitaxel resistance in human epithelial ovarian cancer cells by G2/M phase arrest deterioration, and through c-Src suppression, FV-429 was capable of reversing the resistance by blocking c-Src/Stat3/HIF-1α pathway." (PMID 29324735, 2018). "In summary, our results show that high mRNA expression of all the individual STATs except STAT2 and STAT3 are correlated to a better OS for all the ovarian cancer patients, especially the high level of STAT1 and STAT4 are significantly related to a favorable OS for serous ovarian cancer patients." (PMID 28536310, 2017). "This study collectively suggests that leptin/LEPR signaling via JAK2/STAT3 has the potential to significantly impact on pathogenesis in a subset of ovarian cancer patients who may benefit from strategies that dampen this pathway." (PMID 29212170, 2017). "As a result, a detailed molecular characterization of regulation of MMP-2 could further highlight STAT3 as an effective drug target for ovarian cancer." (PMID 28859117, 2017). "We propose that the strategy of modulating p-STAT3 activity may provide an effective therapeutic approach for treatment of ovarian cancer." (PMID 28859117, 2017). "In this study, we tested our hypothesis that STAT3 regulates MMP-9 gene expression in epithelial ovarian cancer." (PMID 28859117, 2017). "Growing evidences indicate that STAT3 may represent a promising molecular target of gene therapy for ovarian cancer." (PMID 29050266, 2017). "In summary, our findings suggest that the OB3 peptide may prevent leptin-induced ovarian cancer initiation and progression by disrupting leptin-induced proliferative signals via STAT3 phosphorylation and ERα activation." (PMID 28750624, 2017). "Our results support that p-STAT3 may represent a potential therapeutic target in epithelial ovarian cancer." (PMID 28859117, 2017). "In ovarian cancer cells, STAT3 overexpression enhanced glucose consumption and lactate production." (PMID 28445985, 2017). "Amongst the STAT family, STAT3 is the most studied STAT in ovarian cancer." (PMID 28536310, 2017). "In another study using ovarian cancer cells treated with cisplatin under hypoxia, the authors also highlighted the role of STAT3 in this context, however whether HIF-1α is important was not examined." (PMID 29036915, 2017). "In conclusion, these results suggest that the STAT family plays a significant prognostic role in ovarian carcinoma and individual STATs, except STAT2 and STAT3, may act as favorable prognostic markers in ovarian cancer." (PMID 28536310, 2017). "Targeting IL-6, IL-6R or JAK2/STAT3 may offer an efficient management of ascites induced migration and invasion in ovarian cancer patients." (PMID 27825119, 2016). "Par3 could be a candidate for prognostic biomarkers in ovarian cancer in monitoring STAT3 signaling." (PMID 27855669, 2016). "In terms of developing prognostic biomarkers, our study suggests that Par3 could be a candidate for ovarian cancer management, especially in monitoring STAT3 signaling in metastatic ovarian cancer." (PMID 27855669, 2016).
ovarian carcinoma (continued). "Previous studies on ovarian cancer cells have shown that melittin inhibits their growth through induction of apoptosis mediated via inhibition of signal transducer and activator of transcription 3 (STAT3) and activation of Janus kinase 2 (JAK2), both of which are critical during angiogenesis." (PMID 27754384, 2016). "Based on these results, we reasoned that the IL-6/STAT3 pathway might be important for regulating Par3 function in certain types of ovarian cancer cells." (PMID 27855669, 2016). "In addition, immunohistochemical studies were performed to investigate the effects of ONA, and STAT3 activation in the ovarian cancer tissue was decreased by the administration of ONA." (PMID 27404320, 2016). "This study revealed for the first time that inflammatory mediators modulate Wnt5A and ROR2 through NF-kB and STAT3 transcription factors and this may play a role in ovarian cancer cell migration." (PMID 28536612, 2016). "Our current study demonstrate the efficiencies of resveratrol in inhibiting human ovarian cancer cells in terms of remarkable G1 phase accumulation, increased apoptosis fraction and concurrent suppression of Wnt, Notch and STAT3 signaling as well as their downstream cancer-related gene expression." (PMID 25896424, 2015). "It has been reported that Oct4 can regulate signal transducer and activator of transcription 3 (Stat3) expression in embryonic stem cells, while a functional cooperation between Nanog and p-Stat3 translocation was also implied in breast and ovarian cancer." (PMID 25879771, 2015). "Taken together, the results indicate that the blockage of the STAT3 pathway by STAT3 decoy ODN carried by SLN may be a novel strategy for ovarian cancer treatment." (PMID 25923701, 2015). "Constitutive STAT3 activation has been found in ovarian cancer cell lines and clinical specimens." (PMID 25923701, 2015). "In ovarian cancer, high expression levels of STAT3 were shown to promote cisplatin resistance." (PMID 25638155, 2015). "Further studies are required to address whether p-STAT3 could be a potential biomarker to predict the response to gefitinib in ovarian cancer." (PMID 25928246, 2015). "Moreover, verteporfin-PDT induced epidermal growth factor receptor (EGFR) and signal transducer and activator of transcription 3 (STAT-3) signaling in ovarian carcinoma (OVCAR-5) and non-small cell lung cancer (H460) cells." (PMID 26705830, 2015). "The concurrent activation of multiple signaling pathways, including EGFR, PI3/AKT, MEK/ERK and JAK/STAT3, appears to be more common in ovarian cancer and raises an important question about the involvement of these signaling pathways in the development of drug resistance." (PMID 25928246, 2015). "Additionally, it was observed that LPA induces cell motility through STAT-3 phosphorylation in ovarian cancer cells." (PMID 26418031, 2015). "Treatments with Wnt, Notch or STAT3 selective inhibitor reveal that only AG490, a JAK-specific inhibitor, inhibits OVCAR-3 and CAOV-3 cells in the extent as similar as that of resveratrol, suggesting the importance of STAT3 activation in the maintenance and survival of ovarian cancer cells." (PMID 25896424, 2015). "The results demonstrated distinct inhibitory effects of resveratrol on human ovarian cancer cells in terms of remarkable G1 phase accumulation, increased apoptosis fraction and concurrent suppression of Wnt, Notch and STAT3 signaling as well as their downstream cancer-related gene expression." (PMID 25896424, 2015). "In this study, we investigated the mechanism for the limited activity of the EGFR inhibitor, gefitinib, in ovarian cancer cells, and found that increased activity of STAT3 after gefitinib treatment could partially explain the gefitinib resistance." (PMID 25928246, 2015).
ovarian carcinoma (continued). "It is therefore possible that the activated STAT3 signaling is the critical molecular target of resveratrol and this polyphenol compound would be an alternative option in the management of ovarian cancers, especially the ones insensitive to conventional therapeutic drugs." (PMID 25896424, 2015). "We hypothesized the activation of STAT3 could lead to chemotherapeutic resistance in ovarian cancer cells in hypoxic conditions." (PMID 25594014, 2014). "STAT3 is crucial for cancer development and metastasis as well as cancer inflammation and frequently activated in different types of cancers such as breast, lung, renal, prostate, pancreatic, colon, gastric, cervical, and ovarian cancers." (PMID 24976685, 2014). "Furthermore, we have previously demonstrated sustained activation of the STAT3 pathway in advanced-stage ovarian tumors and in cisplatin-treated ovarian cancer cell lines." (PMID 24782986, 2014). "Our current data shows that tyrosine-phosphorylated STAT3 is highly expressed in advanced ovarian cancer and suggests that pSTAT3 Tyr705 may specifically be activated in those ovarian cancers that are hypoxic or have regions of hypoxia." (PMID 25594014, 2014). "Additionally, STAT3 activity is enhanced in paclitaxel-resistant ovarian carcinoma cells to maintain the resistant state of the cells." (PMID 25266665, 2014). "Knock-down of STAT3 by specific siRNA restored cisplatin sensitivity of ovarian cancer cells." (PMID 25006835, 2014). "Similarly, increased activation of STAT3 is a prominent feature in hypoxic regions of ovarian cancers and has been shown to be important for cancer cell survival and proliferation." (PMID 24980820, 2014). "Additionally, STAT3 is involved in EMT in ovarian cancer, and STAT3 phosphorylation is significantly correlated with TNM (tumor, lymph node, and metastasis stages)." (PMID 24789104, 2014). "Notably, the combination of 20 μM CA and PTX inhibited STAT3 activity in the epithelial ovarian cancer cells, though CA alone or PTX alone had lesser effects on the STAT3 activity." (PMID 24260055, 2013). "Since IL-6 is known to be the major cytokine fuelling STAT3 activation in ovarian cancer cells, the inhibitory effect of minocycline on STAT3 activation may be attributed to its IL-6 modulatory effects." (PMID 23593315, 2013). "While several reports recognize STAT3 as an oncogenic factor in ovarian cancer, interestingly there are reports showing that it may play a dual role in some other cancers where it acts as a tumor-suppressor or correlates inversely with metastasis." (PMID 23593315, 2013). "The present study investigated whether corosolic acid (CA), which has been previously reported to be a STAT3 inhibitor, was able to increase the sensitivity to chemotherapeutic drugs in epithelial ovarian cancer cells." (PMID 24260055, 2013). "Since DIM suppressed the activation of STAT3 in ovarian cancer cells, we wanted to test whether DIM can inhibit invasion and angiogenesis." (PMID 22280969, 2012). "In the present study, we provide evidence that DIM induces apoptosis in ovarian cancer cells by blocking the activation of STAT3 and its downstream effector molecules, while IL-6 treatment or overexpression of STAT3 significantly protects ovarian cancer cells from DIM-induced apoptosis." (PMID 22280969, 2012). "A recent study demonstrated that STAT3 is activated in 94% of ovarian cancer patients." (PMID 22280969, 2012). "Furthermore, various reports indicate the role of STAT3 in resistance of ovarian cancer to chemotherapy." (PMID 22280969, 2012). "Supporting our hypothesis, our results show that silencing STAT3 resulted in about 35% apoptosis in SKOV-3 cells suggesting the critical role of STAT3 in ovarian cancer cells." (PMID 22280969, 2012). "We hypothesized that DIM induces apoptosis in ovarian cancer cells by inhibiting STAT3, and then systematically tested our hypothesis." (PMID 22280969, 2012).
ovarian carcinoma (continued). "To further strengthen our observation that DIM-induced apoptosis was mediated by STAT3 inhibition in ovarian cancer cells, we transiently transfected SKOV-3 cells with STAT3 encoding plasmid for 24 h, resulting in an almost twofold increase in the expression of STAT3." (PMID 22280969, 2012). "In addition, to convincingly establish STAT3 as a target of DIM, cells were transfected with STAT3 expression plasmid to activate STAT3 in ovarian cancer cells." (PMID 22280969, 2012). "Also STAT3 is overexpressed in ovarian cancer compared with normal or benign ovarian tumour tissue, and its expression was significantly higher in FIGO stage III/IV compared with stage I/II." (PMID 21694727, 2011). "In contrast, significant inhibition in cell motility was observed within 14 h in EGF-treated cells in the presence of AG490 (100 μM), indicating that JAK2/STAT3 pathway may be involved in the EGF-induced motility of ovarian cancer cells." (PMID 19088723, 2009). "Therefore, the identification of JAK2 activation and increased STAT3 activation in ovarian carcinoma samples is a significant step towards answering this question." (PMID 19088723, 2009). "None the less, the pathogenic role of JAK/STAT signalling pathway has been documented in cancer, the role of JAK2/STAT3 in the pathogenesis of ovarian cancer is still unknown." (PMID 19088723, 2009). "In fact, overexpression of activated STAT3 is found in most paclitaxel-resistant ovarian cancer cells, suggesting that this overexpression may lead to the resulting chemoresistant phenotype." (PMID 18939993, 2008). "Our previous results also indicated that Stat3 is activated in ovarian cancer." (PMID 17311011, 2007). "Stat3, a mediator in inflammatory responses and overexpressed in ovarian cancer, might play an important role in this change in cytokine production by tumor cells suppressing proinflammatory cytokine production." (PMID 16164749, 2005). "Importantly, GA-NPs@DCV exerts potent anti-ovarian cancer effects by promoting immune activation, inhibiting immune evasion through the Stat3/IDO1/AhR signaling axis, and remodeling tumor immune microenvironment via regulation of the tryptophan metabolic pathway." (PMID 41743162, 2026). "Furthermore, combining paclitaxel with the JAK2-selective inhibitor CYT387 in patient-derived ovarian cancer cells suppressed the paclitaxel-induced activation of the JAK2/STAT3 pathway, as well as the expression of CSC and embryonic stem cell markers in the surviving cells." (PMID 40430852, 2025). "Similarly, the level of signal transducer and activator of transcription 3 (STAT3) in sEVs secreted by ovarian cancer cells is elevated, which may contribute to tumor progression and drug resistance." (PMID 40008006, 2025). "Furthermore, IGF2BP1 can promote ferroptosis resistance by stabilizing ferritin heavy chain 1 (FTH1), signal transducer and activator of transcription 3 (STAT3), and parkinsonism-associated deglycase (PARK7) mRNAs in HCC, bladder cancer, ovarian cancer, and GC, respectively." (PMID 40584294, 2025). "Importantly, we observed a synergistic inhibition on STAT3 phosphorylation when we combined both Cryptotanshinone and RGD inhibitors in the presence or absence of OSM stimulation, which suggest that blocking integrin signaling is important for sustained STAT3 signaling in ovarian cancer cells." (PMID 38839865, 2024). "Additionally, exosomes isolated by differential centrifugation from ovarian cancer patients' amniotic fluid or ascites activate Toll-like receptor to boost interleukin-6 (IL-6) production in monocytes and activate the STAT3 pathway in tumor cells, stromal cells, and immune cells." (PMID 38796525, 2024). "Therefore, further studies on the effect of IL-6 blockers in ovarian cancer are needed and elucidating the correlation between IL-6 activated STAT3 phosphorylation and FoxO3a may suggest and exciting new therapeutic directions." (PMID 37047012, 2023).